STING1 (stimulator of interferon response cGAMP interactor 1)
Diseases named in the same sentence as STING1 in open-access papers (continued):
Sharing a sentence is not in itself a finding about the gene and the disease.
infection (732 papers, 2010 to 2026). The state of being infected such as from the introduction of a foreign agent such as serum, vaccine, antigenic substance or organism. "STING1 (also known as transmembrane protein 173) has been associated with infection, inflammation, immunity, autophagy, and cell death." (PMID 38069314, 2023). "Increasing evidence highlights that a dysfunctional STING1 pathway is implicated in sterile inflammation and infection." (PMID 35769880, 2022). "In general, pathogenic DNA can activate STING1 and subsequent autophagy to restrict pathogen infection by removing bacteria and viruses." (PMID 34078874, 2021). "Since STING1 plays a critical role in innate immunity, it is still interesting whether mitochondrial STING1-mediated ferroptosis is implicated in infection and sterile injury." (PMID 34195205, 2021). "Consequently, an insufficient or excessive activation of the STING1 pathway is implicated in various pathological conditions, such as tumorigenesis, infection, disseminated intravascular coagulation, autoimmune conditions, and tissue damage." (PMID 34078874, 2021). "In S. salar, the STING1 transcript exhibited a dynamic response to infection by P. salmonis, marked by an early-phase induction followed by suppression by day five." (PMID 40607404, 2025). "Under the condition of infection, STING1 not only as a regulator of autophagy, but also an autophagy substrate." (PMID 36081940, 2022). "Recent evidence indicated that STING1 played a crucial role in enhancing innate immune signal transduction induced by host DNA damage and pathogen infection." (PMID 36224658, 2022). "The stimulator of interferon response cGAMP interactor 1 (STING1, also known as TMEM173), an ER-associated protein involved in immunity, infection, and coagulation, connects mitochondrial DNA stress to autophagy-dependent ferroptosis." (PMID 32582708, 2020). "In addition, perturbation of Hrf-063 or eIF4A1 altered the expression of STAT1 and CAV1, and Hrf-063 regulated ISG15 and STING1 transcription in a time- and infection-dependent manner." (PMID 42306525, 2026). "STING1-mediated autophagy during infection is also related to NF-κB signaling." (PMID 34078874, 2021). "Together, STING1-dependent autophagic clearance of invading pathogens may be an important host defense mechanism against infection." (PMID 34078874, 2021). "When viral genomic RNA is internalized and released into the cytoplasm after infection, the RNA is recognized by cellular RNA sensors such as stimulator of interferon response cGAMP interactor 1 (STING), Toll-like receptor 7 (TLR7), DExD/H-box helicase 58 (RIG-I), and others." (PMID 32709063, 2020). "As STING1 also promotes autophagy, it may establish negative feedback to control the expression and activation of STING1 during infection." (PMID 35769880, 2022). "The observed upregulation of Mx1, Ifi44, and Sting1 is indicative of type I interferon (IFN-I) pathway activation, often triggered by cellular stress, infection, or cytosolic self-derived mitochondrial DNA (mtDNA)." (PMID 41465333, 2025). "In our study, we could not find a correlation between STING1 expression and sensitivity to infection by oHSV1-FLT3L, which is contradictory to other reports for T-VEC." (PMID 40955425, 2025).
vasculopathy (246 papers, 2015 to 2026). "Gain-of-function variants in STING1 cause the type I interferonopathy STING-associated vasculopathy with onset in infancy (SAVI, MIM: 615934)." (PMID 35126383, 2021).
bacterial infection (98 papers, 2011 to 2026). "Gene ontology (GO) analysis of upregulated genes using Biological Process and KEGG pathways revealed many categories related to immune response against viral and bacterial infection; and immune genes were the most robustly upregulated in response to STING1 activation." (PMID 40195022, 2025). "Macroautophagy/autophagy initiated by STING1 (stimulator of interferon response cGAMP interactor 1) is actively involved in viral infection; and it is known that interferon-inducible guanylate-binding proteins (GBPs) exploit autophagy to defend the host against bacterial infection." (PMID 40396017, 2022). "Whereas Class2 uniquely included pathways related to bacterial infections (e.g., E. coli, Salmonella) together with actin-cytoskeleton and T-cell modules (e.g., ACTB, PFN1, RAC2, PIK3CD, CD3D/CD3G, STING1, TRADD, CASP8, BCL2, HLA-F)." (PMID 41394852, 2025). "Similar to bacterial infection, during herpes simplex virus 1 (HSV-1) infection, cytosolic viral DNA triggers STING1-dependent autophagy in bone marrow-derived DCs46." (PMID 34078874, 2021). "Stimulator of interferon genes (STING; also known as STING1) initiates type I interferon signalling following detection of double-strand DNA (dsDNA) in the cytosol (often a result of viral or bacterial infection)." (PMID 39145464, 2024).
cardiovascular diseases (48 papers, 2019 to 2026). "The genetic deletion of key molecules in this pathway, such as CGAS, STING1, and interferon regulatory factor 3, affords salubrious effects, including improving survival and cardiac dysfunction, rendering the CGAS-STING1 pathway an attractive therapeutic target in cardiovascular disease." (PMID 40180542, 2025).
STING1 also shares sentences with these, for which no sentence is quoted: systemic lupus erythematosus (143 papers); colorectal cancer (115); Aicardi-Goutières syndrome (84); neurodegenerative disease (83); ovarian carcinoma (72); hepatocellular carcinoma (64); colitis (58); gastric cancer (53); infectious disease (52); liver fibrosis (52); Parkinson disease (52); diabetes (45); inflammation (45); amyotrophic lateral sclerosis (43); non-small cell lung carcinoma (43); metabolic disease (41); prostate carcinoma (40); cardiac hypertrophy (39); Alzheimer disease (38); acute kidney injury (37); ischemic stroke (37); atherosclerosis (36); glioblastoma (36); Insulin resistance (34); nonalcoholic fatty liver disease (31); Immunodeficiency (30); HCMV infection (28); head and neck squamous cell carcinoma (28); influenza (28); Stroke (28).
A further 566 diseases each share a sentence with STING1 in 26 papers or fewer.